SPRYD3 (SPRY domain containing 3)
Synonyms: FLJ14800
Tractability: Antibody: the Human Protein Atlas places it where antibodies can reach. PROTAC: ubiquitination databases record sites on it; its protein half-life has been measured.
Gene: Protein-coding gene on chromosome 12 (53,064,316 to 53,079,414, reverse strand). Ensembl gene ENSG00000167778.
Subcellular location (Human Protein Atlas): Cytosol; Nucleoplasm; Actin filaments; Plasma membrane; Vesicles
Gene Ontology:
Molecular function: protein-macromolecule adaptor activity
Genetic constraint (gnomAD): Loss-of-function variants: 17 observed, 49.49 expected, observed/expected ratio (o/e) 0.34, 90% interval 0.23 to 0.51. The upper end of that interval is the gene's LOEUF score, 0.51, which puts it in group 2 of 6, group 1 being the genes least tolerant of losing a copy. Missense variants: 392 observed, 588.31 expected, observed/expected ratio (o/e) 0.67, 90% interval 0.61 to 0.72. Synonymous variants: 194 observed, 216.08 expected, observed/expected ratio (o/e) 0.9, 90% interval 0.8 to 1.01.
Homologues: Orthologues: chimpanzee SPRYD3 (100% identical), macaque SPRYD3 (100% identical), mouse Spryd3 (99% identical), rat Spryd3 (99% identical), pig SPRYD3 (99% identical), guinea pig SPRYD3 (99% identical), dog SPRYD3 (92% identical), rabbit SPRYD3 (87% identical), tropical clawed frog spryd3 (77% identical), zebrafish spryd3 (72% identical), Caenorhabditis elegans gid-1 (28% identical). Paralogues in human: RANBP9 (24% identical), RANBP10 (24% identical), GID8 (8% identical).
Diseases named in the same sentence as SPRYD3 in open-access papers:
SPRYD3 is named in the same sentence as 2 diseases in open-access papers, as found by Europe PMC text mining. Sharing a sentence is not in itself a finding about the gene and the disease.
SPRYD3 shares sentences with these, for which no sentence is quoted: cancer (1 paper); glioblastoma (1).